SAMHD1 (SAM and HD domain containing deoxynucleoside triphosphate triphosphohydrolase 1)
Diseases named in the same sentence as SAMHD1 in open-access papers (continued):
Sharing a sentence is not in itself a finding about the gene and the disease.
cancer (continued). "This study suggests that SAMHD1 mutations can contribute to the intracellular dNTP level elevation commonly observed in cancer cells." (PMID 34492268, 2021). "Overall, our study reveals that loss of dNTPase activity induced by SAMHD1 R366 cancer mutations can mechanistically contribute to the elevated intracellular dNTP pools commonly observed in cancer cells." (PMID 34492268, 2021). "Because we identified R-loops as an endogenous source of genome instability in SAMHD1 deficiency, we focused on the association between SAMHD1 expression and cancer development." (PMID 33857133, 2021). "A majority of the SAMHD1 cancer-associated mutations tested were found to be structurally destructive, consistent with SAMHD1 mutations observed in patients with AGS." (PMID 34492268, 2021). "Future studies are expected to better characterize the physiological and pathological R-loops and SAMHD1-deficiency derived R-loops in cancer development." (PMID 33857133, 2021). "To investigate the impact of cancer-associated mutations on SAMHD1 functions, we searched for SAMHD1 mutants showing WT-level cellular protein stability." (PMID 34492268, 2021). "Recent identification of mutations in SAMHD1 in various cancer cell types generated a unique opportunity to understand the role of dNTP hydrolysis and its regulation in the elevated intracellular dNTP pools observed in cancer cells." (PMID 34492268, 2021). "This study suggests that the loss of SAMHD1 dNTPase activity induced by R366 mutations can mechanistically contribute to the elevated dNTP levels commonly found in cancer cells." (PMID 34492268, 2021). "Among AGS-associated genes, SAMHD1 is most frequently mutates in various types of tumors and malignancies, suggesting that it is biologically relevant to cancer development." (PMID 33857133, 2021). "As a negative regulator of both intercellular dNTPs and DNA replication stress, SAMHD1 is directly implicated in several cancers." (PMID 32244340, 2020). "More recently, SAMHD1 has been implicated in the protection against cancer and chronic inflammation by limiting the release of single-stranded DNA." (PMID 32197329, 2020). "Samhd1, for example, encodes a protein that regulates intracellular dNTP levels and DNA damage repair and shows tumor suppressive functions in many cancer types." (PMID 32831131, 2020). "SAMHD1 mutations are associated with the autoimmune disease Aicardi–Goutières syndrome and hypermutated cancers." (PMID 32576829, 2020). "Cancer-associated mutations, which are scattered throughout the SAMHD1 gene, have been found to modulate in vivo SAMHD1 activity and expression levels." (PMID 32244340, 2020). "SAMHD1 somatic mutations have been identified in several cancers, including solid cancers such as glioblastoma, colorectal, lung, and pancreatic cancers and blood-related malignancies such as CLL and myeloma." (PMID 31547393, 2019). "SAMHD1 mutations have been shown to alter cellular dNTP concentrations and are associated with the development of certain cancers (reviewed comprehensively by Mauney and Hollis)." (PMID 31296733, 2019). "Here, we present evidence that DNA damage induced by topoisomerase inhibitors used in cancer treatment is associated with SAMHD1 dependent inhibition of HIV‐1 infection in primary human MDM." (PMID 29084722, 2018). "SAMHD1 mutations occur in leukemias and other types of human cancer, suggesting that a surplus of dNTPs contributes to cell transformation by affecting the fidelity of DNA synthesis." (PMID 30039733, 2018). "Intriguingly, cancer prone mutations in SAMHD1, which is required for replication fork stability and regulation of Mre11-dependent degradation of nascent DNA, activate the IFNγ pathway promoting cancer development." (PMID 29950452, 2018). "SAMHD1 acetylation levels are highest during G1 phase and facilitates G1/S transition, causing increases in cell growth and colony formation in cancer cells." (PMID 28978134, 2017).
cancer (continued). "By identifying the specific acetylation site of SAMHD1 and mutating it to block its acetylation, we aimed to discover a novel function of SAMHD1 acetylation in cancer cell growth." (PMID 28978134, 2017). "A tumor suppressor role for SAMHD1 has been proposed based on its maintenance of genome integrity and cancer associations with downregulation." (PMID 28061811, 2017). "Further functional analyses of SAMHD1 mutations identified in human cancer cells would aid in answering these important questions." (PMID 26416562, 2015). "Impaired SAMHD1 function can cause increased dNTP pool resulting in genomic instability and cell-cycle progression, thereby facilitating cancer cell proliferation." (PMID 26416562, 2015). "Mutations in SAMHD1 have been identified in malignant B-cells isolated from chronic lymphocytic leukaemia patients and in other types of cancer." (PMID 24854580, 2014). "One possible explanation could be variants in the SAMHD1 gene, which have been implicated in both delayed ovarian aging and increased cancer risk." (PMID 41158883, 2025). "Although molecular mechanisms underlying TCP1 role in promoting cancer are unknown, our data point towards SAMHD1 as a key factor, confirming the prognostic value of SAMHD1 through the modulation of TCP1 levels, which may putatively also affect IL signaling." (PMID 37667113, 2024). "This is partly linked to the expression of SAMHD1 in cancer cells." (PMID 39089813, 2024). "Considering its role in DNA damage repair, SAMHD1 might be implicated in tumorigenesis and response to chemotherapy in cancer." (PMID 37081042, 2023). "Indeed, an SAMHD1 knockout study revealed that SAMHD1 controls cell cycle status and apoptosis in a myeloid cell line, and many mutations found in cancer cells induce the loss of its dNTPase activity." (PMID 37567474, 2023). "SAMHD1 mutations are found in multiple cancers and have been linked to resistance to chemotherapy." (PMID 37009792, 2023). "Recently, SAMHD1 was reported to be associated with cancer progression." (PMID 37009792, 2023). "Furthermore, SAMHD1 levels positively correlates with USP7 in various human carcinomas, and is associated with an unfavorable survival outcome in patients who underwent chemotherapy." (PMID 37081042, 2023). "Our findings in human cancerous tissues suggest that SAMHD1 might be implicated in early-stage carcinomas to overcome elevated DNA damage and oncogenic stress." (PMID 37081042, 2023). "Therefore, future studies are needed to characterize SAMHD1-mutated cancer types and accompanying mutations in other, potential driver genes." (PMID 34480199, 2022). "In some types of cancer, it could therefore be more difficult to identify SAMHD1 as a potential driver gene merely based on mutation frequency." (PMID 34480199, 2022). "Consequently, it is important to understand in which specific types of cancer and/or disease stages SAMHD1 mutations or expression level variations (e.g., through epigenetic changes) would promote malignant initiation and/or progression." (PMID 34480199, 2022). "Additionally, SAMHD1 was identified to be recurrently mutated in certain hematological malignancies (“blood” cancer) and analyzed in detail as outlined in the next paragraph." (PMID 34480199, 2022). "Similarly, no relevant differences were observed between wild type and KO cells in cell cycle profile and expression of main genes and pathways associated to molecular mechanisms of cancer, except for the different expression of SAMHD1 protein." (PMID 35158911, 2022). "One could hypothesize that SAMHD1, if mutated or downregulated in cancer cells, would lead to accumulating self-DNA that might be sensed through the cGAS-STING pathway thus inducing a tumor-associated chronic inflammatory response." (PMID 34480199, 2022). "Therefore, in this review, our aim is to provide a detailed overview of the cancers that are affected by SAMHD1 and to summarize the reported mutations and corresponding functional consequences." (PMID 34480199, 2022).
cancer (continued). "Additionally, in many cancers, high expression levels of SAMHD1 are associated with a more favorable outcome." (PMID 34480199, 2022). "As described, initial indications that SAMHD1 mutations might be involved in cancer development/progression were derived from the occurrence of early-onset CLL in an AGS patient." (PMID 34480199, 2022). "To understand whether differences in mtDNA-CN levels between SAMHD1 mutation carriers was a consequence of cancer diagnosis, we repeated association testing with mtDNA-CN excluding cancer patients." (PMID 35023831, 2022). "We found 1542 mutations of SAMHD1 affecting 957 donors across 65 cancer projects." (PMID 34480199, 2022). "Moreover, the high expression level of SAMHD1 had an independent significant association with unfavorable OS in some types of cancer." (PMID 35978833, 2022). "This suggests that SAMHD1 mutations contribute to the elevation of intracellular dNTP levels commonly observed in cancer cells and mechanistically connects the respective roles of SAMHD1 in cancer and HIV-1 restriction." (PMID 35893688, 2022). "Importantly, changes in SAMHD1 protein functions and/or expression levels due to deleterious mutations can have significant influence on the therapeutic outcome of specific cancer treatments (see last section of this review)." (PMID 34480199, 2022). "Cancer-related, dNTPase-inactivating mutations in SAMHD1 might act in concert with other genetic defects (e.g., in DDR pathways like MMR) to promote a so-called mutator phenotype." (PMID 34480199, 2022). "Interestingly, SAMHD1 mutations have been identified in a variety of cancers, including leukemias, lymphomas, lung cancer, and colon cancer." (PMID 35893688, 2022). "Our results reveal a novel role for SAMHD1 in DNA end joining and provide new insights into how loss of SAMHD1 may contribute to genome instability and cancer development." (PMID 33591315, 2021). "Furthermore, downregulation of SAMHD1 expression is associated with various types of cancer and poor survival rate." (PMID 33857133, 2021). "As dNTP levels in cancer cells are 6 to 11-fold higher than that of normal cells, we hypothesized that cancer-associated SAMHD1 mutants would have reduced dNTPase activity, ultimately elevating intracellular dNTP levels." (PMID 34492268, 2021). "These low protein levels could be indicative of structural alterations, which makes it difficult to investigate the mechanistic and functional alternations made by the SAMHD1 cancer mutations." (PMID 34492268, 2021). "Moreover, we suggest that SAMHD1 and R-loop are novel diagnostic markers and targets for patient stratification in anti-cancer therapy." (PMID 33857133, 2021). "However, it is unclear how these SAMHD1 mutations mechanistically contribute to cancer cell phenotypes." (PMID 34492268, 2021). "Several SAMHD1 cancer-related mutations were shown to have a loss in negatively modulating LINE-1." (PMID 32244340, 2020). "Furthermore, SAMHD1 sensitises cancer cells to nucleoside-analogue anti-cancer therapies and is linked with DNA repair and suppression of the interferon response to cytosolic nucleic acids." (PMID 32576829, 2020). "This can be exploited to selectively kill cancer cells that acquired SAMHD1 mutations." (PMID 32402273, 2020). "Finally, a series of SAMHD1 mutations were also reported in various cancer cell types while why SAMHD1 is mutated in these cancer cells remains to investigated." (PMID 32244340, 2020). "Deregulation of these proteins at telomeres might play an unrecognized role in the development of cancer, as exemplified by SAMHD1, which has been found mutated in cancer cells and seems to have a pivotal function in the preservation of telomere integrity." (PMID 30456372, 2018). "Because SAMHD1 can control the availability of dNTPs and cell cycle progression, it is likely associated with cancer; however, little has been investigated about its role in cancer proliferation." (PMID 28978134, 2017).
cancer (continued). "Chronic low-level DNA damage and enhanced sensitivity to genotoxic stress also suggest that patients with TREX1 mutations may have an increased cancer risk, like patients with SAMHD1 mutations." (PMID 27230542, 2016). "Mutations of SAMHD1 have been identified in several human cancers." (PMID 26416562, 2015). "Furthermore, the role of SAMHD1 in tumorigenesis and the underlying mechanisms of SAMHD1-mediated cancer progression remain unknown." (PMID 37009792, 2023). "Nevertheless, the pattern of cancer-related mutations that are found throughout the sequence of SAMHD1 together with the fact of its downregulation in several tumors rather indicates that SAMHD1 might act as a tumor suppressor." (PMID 34480199, 2022). "Notably, SAMHD1 has also been reported to protect cells from build‐up of cytotoxic dGTP, which could be exploited to target SAMHD1‐deficient cancer cells with PNP inhibitors." (PMID 35583750, 2022). "However, the precise molecular mechanisms underlying these observations are unclear at present, and SAMHD1 influence in cancer onset, progression and/or treatment efficacy remain largely unknown." (PMID 35158911, 2022). "However, the unaltered cellular expression of R366C and R366H allowed us to use these mutants as a tool for investigating which functions of SAMHD1 may be implicated in the enzyme's role in cancer cells." (PMID 34492268, 2021). "Our findings suggest that SAMHD1 functions as a tumor suppressor by resolving R-loops, and thus, SAMHD1 and R-loop may be novel diagnostic markers and targets for patient stratification in anti-cancer therapy." (PMID 33857133, 2021). "Thus, the increased level of SAMHD1 acetylation during G1 phase may cause sufficiently low levels of dNTPs for G1/S transition, which in turn promotes cancer cell proliferation." (PMID 28978134, 2017). "SAMHD1-deficient mice have a dNTP imbalance, with higher intracellular dATP and dGTP concentrations than dTTP and dCTP concentrations, and a cellular dNTP imbalance can promote higher rates of mutagenesis in cancer cells, and influence the ability of DNA viruses to infect cells." (PMID 28046007, 2017). "However, it remains unclear whether AGS patients with SAMHD1 mutations have a higher predisposition to cancer development." (PMID 26416562, 2015). "Herein, we identified that increased SAMHD1 expression levels correlate with poor prognosis across multiple cancer types, and that SAMHD1 is upregulated in a variety of tumors." (PMID 41392286, 2025). "SAMHD1 has, therefore, emerged as a crucial biomarker for the anti-cancer effects of PNP inhibitors." (PMID 40519286, 2025). "The role of SAMHD1 in cancer, particularly its contribution to drug resistance, has gained increasing attention in recent years." (PMID 41392286, 2025). "Recently, SAMHD1's role in cancer has gained attention due to aberrant expression levels and mutations reported in multiple malignancies." (PMID 39679869, 2025). "ARD1-mediated K405 acetylation promoted SAMHD1 dNTPase activity and promoted cell proliferation of cancer cell lines (including HeLa and A549) by increasing G1/G0 phase transition." (PMID 40277359, 2025). "This cooperative effect between SAMHD1 silencing and radiotherapy represents a potential therapeutic strategy for improving cancer treatment outcomes." (PMID 40629041, 2025). "Selectively depletion of SAMHD1 in tumors holds the potential to enhance the efficacy of various anti-cancer therapies and promotes innate immune activation, which in turn benefits the host’s anti-tumor immune responses." (PMID 41392286, 2025). "Cellular DHFR activity is required for cancer cells and the cellular SAMHD1 protein is a tumor suppressor whose expression is reduced in cancer cells." (PMID 39339888, 2024).
cancer (continued). "Subsequently, more studies have identified the involvement of SAMHD1 in innate immunity, inflammatory response, and cancer development; however, the role of SAMHD1 in renal rejection and long-term survival of transplanted kidneys has not yet been elaborated." (PMID 38874084, 2024). "SAMHD1 expression was significantly increased upregulated in cancer tissues compared to normal tissues in RCC among several cancer types." (PMID 37009792, 2023). "For further confirmation, we analyzed the correlation between SAMHD1 and cortactin phosphorylation in paired cancer and normal tissues from patients with ccRCC." (PMID 37009792, 2023). "For example, SAMHD1 binds to another protein and promotes the formation of lamellipodia, protrusions on the leading edge of the cancer cell membrane that aid migration, by inducing a particular signaling pathway." (PMID 37009792, 2023). "Both SAMHD1 and phosphorylated cortactin levels were higher in cancer tissues than in adjacent normal tissues." (PMID 37009792, 2023). "We then analyzed the potential prognostic significance of SAMHD1 expression in patients with various cancers who received chemotherapy according to TCGA data." (PMID 37081042, 2023). "Among the several types of cancer, the difference in SAMHD1 expression between cancerous and normal tissues was the highest in pankidney cancer." (PMID 37009792, 2023). "A significant positive correlation between USP7 and SAMHD1 expression was identified in all three tumor types, suggesting that the existence of the USP7-SAMHD1 axis in various human cancers." (PMID 37081042, 2023). "Analysis of protein levels according to cancer grades indicated that SAMHD1 was overexpressed in tumor tissues with intermediate and poor prognoses." (PMID 37009792, 2023). "Further, SAMHD1 is upregulated in various early-stage human carcinomas and positively correlated with USP7." (PMID 37081042, 2023). "Here, we show that SAMHD1 is up-regulated in early-stage human carcinoma tissues and cell lines under oxidative stress or genotoxic insults." (PMID 37081042, 2023). "Attesting to the function, both USP7 and SAMHD1 proteins were highly expressed in human carcinomas of various organs and their expressions were positively correlated." (PMID 37081042, 2023). "We found that GBM tumors and GBM-derived cancer cell lines express a high level of SAMHD1, demonstrating its potential importance for this highly lethal cancer." (PMID 36139652, 2022). "Acetylation of SAMHD1 at lysine 405 (K405) increases deoxynucleoside triphosphatase (dNTPase) activity and promotes cancer cell proliferation." (PMID 35803902, 2022). "Moreover, imbalanced dNTP levels due to SAMHD1 function dysregulation might be associated with the rate of replication fork formation under DNA replication stress, leading to gene mutations, genomic instability, and cancer development." (PMID 35158911, 2022). "Both shreds of evidence support our results, demonstrating that SAMHD1 plays a critical role in the response of cancer cells to DSB-inducing agents as platinum derivatives." (PMID 35158911, 2022). "SAMHD1 expression has been shown to regulate the response of cancer cells to cytarabine (ara-C), arabinosylguanine (AraG), and 2′-C-cyano-2′-deoxy-1-β-D-arabino-pentofuranosyl-cytosine (CNDAC)." (PMID 35893688, 2022). "One instance in which there is a clear utility in targeting SAMHD1 in cancer is to improve the efficacy of a commonly used group of chemotherapies, antimetabolites, specifically nucleobase and nucleoside analogues." (PMID 35583750, 2022). "Additional studies should interrogate this further, and also the wider applicability of this strategy, for instance to other nucleoside‐based drugs under SAMHD1 control in cancer cells." (PMID 35583750, 2022). "Due to SAMHD1 central role in cellular dNTP metabolism, its involvement in cancer development has been extensively investigated, albeit its specific role is somewhat controversial." (PMID 35158911, 2022).